INS (insulin)
Diseases named in the same sentence as INS in open-access papers (continued):
Sharing a sentence is not in itself a finding about the gene and the disease.
Insulin resistance (continued). "Analyses of 6 h fasted blood glucose and insulin levels revealed that, although blood glucose levels did not increase with age in mice on CD, insulin levels increased progressively with age indicating the development of age-related insulin resistance in mice fed CD." (PMID 34795407, 2021). "HOMA-IR index, widely used as an insulin resistance index, was increased significantly in HFD-fed mice, and iron administration could not reverse the trend, suggesting the possibility of decreased insulin sensitivity after iron supplementation." (PMID 34441564, 2021). "After 12 months of TRE, body mass was reduced by 3.4% and inflammatory markers (IL-6, IL-1β, and TNF-α), lipid profile (HDL, LDL, TG), and insulin resistance (fasting glucose, insulin, HOMA-IR) significantly improved compared with ND without affecting muscle performance." (PMID 34649266, 2021). "Once insulin resistance is developed, stress-responsive pathways such as JNK are activated, and regulatory cytokine expression or direct oxidative damage of interconnected proteins are increased, while this OS can also hamper the insulin sensitivity in response to insulin-related signaling pathways." (PMID 34885698, 2021). "The reasons for different correlations being found between fasting insulin or HOMA-–IR and serum sclerostin may be related to differences in study population and/or issues with the validity of surrogate markers for insulin resistance in children and adolescents." (PMID 34572220, 2021). "However, one study reported an increase in fasting plasma glucose, and two studies reported a decrease in insulin resistance, assessed as fasting plasma insulin, HOMA-IR (Homeostatic Model Assessment for Insulin Resistance) and HOMA-B (Homeostasis Model Assessment of β-cell dysfunction)." (PMID 34262926, 2021). "Furthermore, the homeostatic model assessment for insulin resistance (HOMA-IR) suggested that LKO mice had significantly higher systemic insulin sensitivity than controls, despite the disruption to hepatic insulin signaling." (PMID 33718833, 2021). "In addition, the findings of this study demonstrated that the patients with classic PCOS phenotype had central obesity; and higher level of insulin and insulin resistance despite lack of BMI difference with other phenotypes." (PMID 33750349, 2021). "This index was derived in a similar way to the homeostatic model assessment for insulin resistance (HOMA-IR), which is based on multiplying the glucose concentration by the insulin concentration and then dividing by a factor (product of mean glucose and insulin values), which normalises to 1.0." (PMID 34813621, 2021). "Growing scientific evidence shows obesity-related conditions such as insulin resistance, type 2 diabetes, and the metabolic syndrome as well as obesity-related systemic markers (e.g., leptin, adiponectin, SHBG, insulin and the IGF axis and C-reactive protein) are associated with breast cancer." (PMID 34066392, 2021). "Moreover, no measurements of insulin or insulin resistance were taken in this study, so that our claims remain limited to the association between blood glucose levels and dopamine signaling." (PMID 34544031, 2021). "Concerning insulin signaling, IR and p85α are targets of some assessed miRNAs, but, according to our data, only miR-149-5p or miR-375-3p regulation would explain the decrease in expression observed after 18 weeks on the HFD and, as a consequence, the insulin resistance." (PMID 34850865, 2021). "Furthermore, EVs from insulin-resistant muscles of palmitate-treated mice influence gene expression and proliferation, but not GSIS, in mouse β cells, contributing to β cell mass adaptation during insulin resistance." (PMID 33539327, 2021). "Whether elevated insulin concentrations and insulin resistance impact the manifestation of TB in patients without T2D remains to be elucidated." (PMID 34835407, 2021).
Insulin resistance (continued). "Particularly, hyperprolactinemia is associated with disorders of glucose and insulin metabolism, clinically translated in impaired glucose tolerance, insulin resistance, and postprandial hyperinsulinemia together with reduced insulin sensitivity either in obese or non-obese patients." (PMID 34917030, 2021). "On the contrary, the level of the glucose, the lipid profiles recorded in the blood, the abdominal fats, the insulin level and the insulin resistance index of rats chronically exposed to D-tagatose were not significantly different from those recorded in the control group (p > 0.05)." (PMID 33928123, 2021). "Additionally, repeated streptozotocin injections induced hyperglycemia without insulin-dependency mimicking a late-type 2 DM with insulin resistance as seen in patients." (PMID 34510273, 2021). "In metabolic syndrome patients, in the absence of glucose, insulin homeostasis disturbances and insulin resistance led to high amounts of polyunsaturated fatty acids (18 : 2 n6, 18 : 3 n3, 22 : 4 n6) and lower concentrations of SFA (12 : 0, 14 : 0, 16 : 0, 17 : 0) in plasma." (PMID 34007967, 2021). "Even more profound is that non-obese individuals above the age of 60 show a distinct impairment in insulin release coupled with subtle insulin resistance, as opposed to elderly individuals, and have marked insulin resistance even in the presence of adequate levels of insulin in circulation." (PMID 34067715, 2021). "Our study has shown a synergistic effect of metformin in combination with MI plus DCI in women with PCOS and insulin resistance in terms of improvement in cycle irregularity, global acne score, LH levels, LH:FSH ratio, lipid profile including cholesterol, HDL and LDL levels and postprandial insulin." (PMID 34268040, 2021). "Improved insulin sensitivity from RAGE−/−-HFD mice is unlikely to be explained by lower insulin-stimulated AKT in AT, which demonstrated that high-fat diet-induced insulin resistance in RAGE deficient adipose tissue does not coincide with a reduction in AKT phosphorylation." (PMID 34686659, 2021). "Because low SHBG is associated with high insulin resistance and high insulin values regardless of weight, low SHBG levels might serve as an indicator of hyperinsulinism and insulin resistance." (PMID 33918160, 2021). "Additionally, insulin resistance has recently been shown to develop in the brains of those with AD, with impaired insulin signaling observed in non-diabetic patients as well." (PMID 33800340, 2021). "This lack of effect of PBA may be due to a severe insulin resistance, too high to detect differences by a conventional dose of insulin when performing the ITT." (PMID 34088954, 2021). "Fasting blood glucose and insulin levels in the HFD-fed mice were significantly higher (90 and 201.3%, respectively) compared to the ND fed mice, and consequently the HOMA-IR value was significantly greater in the HFD group, demonstrating the presence of insulin resistance." (PMID 34406209, 2021). "However, contrasting findings were observed in liver-specific Atg7 knockout mice, which displayed protection from diet-induced obesity and insulin resistance, although this study did not examine insulin signaling in the liver." (PMID 34336862, 2021). "Moreover, 24-month changes in plasma insulin and insulin resistance were numerically greater in non-diabetic subjects following the LC diet, but smaller in patients with type 2 diabetes, compared with the Med diet." (PMID 33919503, 2021). "This large study provides additional evidence that insulin resistance may be the earliest defect and thus highly predictive of dysglycemia; unfortunately, the study did not assess insulin clearance." (PMID 34206745, 2021). "Furthermore, the evaluation of fasting plasma insulin (FPI) and homeostatic model assessment of insulin resistance (HOMA-IR) could predict the early development of IR." (PMID 33445629, 2021).
Insulin resistance (continued). "For instance, astragaloside IV increased basal and insulin-stimulated glucose uptake in C2C12 myotubes and decreased the mRNA expression of inflammatory cytokines through suppression of the IKK/IκBα pathway activation in insulin resistance model of C2C12 myotubes." (PMID 33790972, 2021). "Taken together, these results demonstrate that the mice model with obvious impaired insulin secretion but not insulin resistance exhibits reduced amount of A. muciniphila and replenishment with viable A. muciniphila restores insulin secretion and improves glucose tolerance." (PMID 34085773, 2021). "When insulin secretion fails to balance insulin resistance, impaired glucose tolerance develops, which might subsequently lead to GDM45." (PMID 34650136, 2021). "It should be noted that insulin sensitivity expressed as HOMA-IR and QUICKI indices cannot be considered as a replacement for direct measurement of insulin resistance, but both provide a reliable approximation of direct measures of insulin resistance in rodents and humans." (PMID 34943108, 2021). "Similar effects of diminished MFN2 expression were observed in the liver and muscle cells in animal models of high-fat diet-induced obesity and insulin resistance, which supports the hypothesis that MFN2 can affect insulin signaling and insulin sensitivity through mitochondria-related mechanisms." (PMID 33815291, 2021). "There was a clinical trial reported that intermittent fasting reduced fasting insulin and insulin resistance, while another study found that although intermittent fasting groups lost weight, fasting glucose, fasting insulin, and insulin resistance were not improved." (PMID 34256832, 2021). "Considering that the insulin level could stratify the DRE patients and controls, we further subgrouped patients according to a cutoff value for the HOMA-IR ≥ 2.4, which represents the status of insulin resistance." (PMID 34574891, 2021). "Although research utilizing TRX in individuals with T2D is lacking, the decreases in FBS, insulin concentrations, and insulin resistance found after TRX training with and without taurine supplementation in the present study are in agreement with a prior report in women with PCOS." (PMID 34836211, 2021). "Although we did not measure insulin resistance per se, we can hypothesize that the group with HbA1C > 7% is more insulin resistant as they are more obese and show higher glycemia levels though intensively treated." (PMID 33608002, 2021). "However, elevated fasting insulin level is not a reliable marker for insulin resistance since it reflects not only insulin resistance but also insulin secretion and insulin clearance by the liver." (PMID 34677406, 2021). "Moreover, we have recently shown that palmitic acid (PA) but not palmitoleic acid (POA) induces insulin resistance by decreasing insulin-induced Akt phosphorylation in human umbilical endothelial cells." (PMID 33562475, 2021). "Because insulin-induced GLUT4 translocation is defective in the type 2 diabetic heart, signaling pathways involved in contraction-induced GLUT4 translocation may contain suitable targets to increase cardiac glucose utilization during insulin resistance." (PMID 33090289, 2021). "The insulin value was not measured in this study, so insulin resistance is unclear." (PMID 34334135, 2021). "Therefore, we assessed insulin’s ability to stimulate AKT phosphorylation in tanycytes of mice, which had been fed a high-fat diet (HFD) for 14 weeks and which exhibited increased body weight, adiposity, systemic insulin resistance and glucose intolerance." (PMID 34931084, 2021). "We failed to observe the significant difference in phenotypes from either liver insulin resistance or acute liver failure between WT and SND1 LKO mice, even though there is somewhat an improved effect of SND1 on the activation of the Akt pathway upon insulin stimulation in the liver from HFD-mice." (PMID 34608846, 2021).
Insulin resistance (continued). "Apart from the associations of the genetic models of the eNOS knockout mice and the DDAH1 transgenic mice with insulin sensitivity noted earlier, it has been shown that infusion of the NOS-inhibitor N-monomethyl L-arginine (L-NMMA) in rats induced hypertension and insulin-resistance." (PMID 34492019, 2021). "However, in patients with insulin resistance, insulin failed to increase cAMP levels within platelets, thus impairing its anti-aggregational effects." (PMID 34072487, 2021). "Additionally, HOMA2 does not have an accepted reference range to define normal insulin sensitivity versus insulin resistance compared to other models." (PMID 34884295, 2021). "Although vitamin C may be beneficial to the components or complications of MetS (e.g., decreased blood pressure, glucose, insulin, insulin resistance, etc.), it is not necessarily a reflection of MetS prevention." (PMID 34692744, 2021). "AMPK-mediated GLUT4 translocation is induced by exercise in a mechanism independent of insulin and thus may mitigate the effects of insulin resistance." (PMID 34861815, 2021). "In the same way, pro-inflammatory cytokines participate in insulin resistance in the adipose tissue via the activation of IκB kinase and c-Jun N-terminal kinase, responsible for dephosphorylating the serine of the insulin receptor substrate-1 (IRS-1), turning insulin into less efficient." (PMID 34829598, 2021). "The present study demonstrates the role of dietary strawberries at a daily dose of two-and-a-half servings in decreasing serum insulin and concomitant insulin resistance (HOMA-IR), but not fasting glucose in obese adults with features of the metabolic syndrome." (PMID 33922576, 2021). "On the other hand, other clinical studies have shown that metformin improves endothelial dysfunction irrespective of insulin sensitivity or body weight, suggesting that metformin improves endothelial function through multiple mechanisms, some of which are independent of insulin resistance." (PMID 34439553, 2021). "Importantly, PBA treatment did reduce the fasting insulin levels in Avy and Avy hIAPP mice, illustrating a partial amelioration of insulin resistance that was not uncovered by the ITTs." (PMID 34088954, 2021). "Due to the changes in gravid uterine mitochondrial function and homeostasis in response to hyperandrogenism and insulin resistance, we asked whether flutamide might rescue the mitochondrial morphological and functional defects in the gravid uterus induced by DHT + INS exposure." (PMID 34180022, 2021). "Several surrogate indices (e.g., homeostasis model assessment (HOMA), quantitative insulin sensitivity check index (QUICKI), Matsuda, McAuley, Belfiore, Cederholm, Avignon, and Stumvoll indexes) have been developed as alternative measures of insulin resistance or sensitivity." (PMID 34836231, 2021). "In a previous study, mice with Prkce ablation and 16 weeks of fat feeding did not exhibit reversed diet-induced inhibition of insulin signaling in the liver; thereby, PKCε-independent mechanisms might maintain long-term insulin resistance." (PMID 34850865, 2021). "While these studies indicate that overnutrition dysregulates autophagy in WAT, it is not clear whether dysregulated autophagy impairs insulin sensitivity or is a consequence of insulin resistance." (PMID 34336862, 2021). "Insulin and insulin resistance were not able to be analyzed in our review." (PMID 34543302, 2021). "Additionally, we did not measure blood insulin levels and evaluate the insulin resistance status of study participants." (PMID 34490362, 2021). "This anthropometric marker could thus serve as an adjunct marker for detecting insulin resistance and compensatory hyperinsulinemia in primary care settings where more extended testing such as postprandial glucose and insulin assays are not available." (PMID 33859227, 2021).
Insulin resistance (continued). "Thus, the paradox in hepatic insulin resistance is that insulin fails to suppress hepatic glucose production, nevertheless it continues to stimulate lipogenesis, causing hyperglycemia, hyperlipidemia, hepatic steatosis, and T2DM." (PMID 34284789, 2021). "Our present analysis could not find strong signals of publication bias effects on the insulin levels and insulin resistance, lipid profile, and inflammatory factors except for FPG." (PMID 33865313, 2021). "Pregnancy is a potential risk of glucose intolerance, and insulin sensitivity is further decreased with progression of time till the point of non-matching between the secreted insulin and insulin resistance is reached to declare occurrence of gestational diabetes." (PMID 34290797, 2021). "Furthermore, the levels of fasting plasma glucose, TG, NEFAs, and insulin, which are indicators of insulin resistance, were not different between Tg and WT mice after HFD challenge." (PMID 33262218, 2021). "We cannot rule out the possibility that exercise-induced insulin sensitivity improvement in obese mice with insulin resistance could be due to decreased adiposity secondarily." (PMID 34234788, 2021). "However, HFD-induced obesity and insulin resistance reveal hyperinsulinemia, insulin resistant and hyperglycemia without β-cell failure or insulin depletion." (PMID 34673835, 2021). "Obese individuals may develop insulin resistance and/or glucose intolerance without ever becoming diabetic as long as they compensate by secreting more insulin and expand a non-deleterious adipose tissue." (PMID 35008750, 2021). "In addition, insulin may reduce ABCA1 expression levels in adipocytes, resulting in insulin resistance." (PMID 34975757, 2021). "As non-diabetic patients are able to compensate insulin resistance by increasing insulin secretion, it seems logical to assume that the presence of stress hyperglycemia could imply some degree of pre-existing β-cell dysfunction." (PMID 33981655, 2021). "Insulin resistance means that insulin does not function properly in the target tissue." (PMID 34735502, 2021). "Insulin resistance is a condition that precedes T2DM and, together with genetic and environmental factors, such as obesity and physical inactivity, may lead to the failure of β-cell function and, hence, a progressive decline in insulin secretion." (PMID 33572228, 2021). "However, under obese conditions, targeting skeletal muscle IKKβ can only alleviate local insulin resistance, but not systemic insulin responsiveness." (PMID 34957242, 2021). "The other—a cross-sectional study from Belgium—revealed significant inverse associations between maternal pre-pregnancy BMI (mppBMI) and proinsulin, β-cell function, fasting insulin (for females only), and insulin resistance (for females only), but not with fasting plasma glucose." (PMID 33902746, 2021). "We can hypothesize that the preferential storage of fat within the SATafter RYGB is important in preventing insulin resistance, T2DM, and steatohepatitis.The observed normal HOMA-IR values and serum glucose, insulin, ALT, and AST levelsafter RYGB reflect an improved metabolic status." (PMID 34878062, 2021). "This could be related with the observation that despite high insulin and hepatic insulin resistance, the fKO mice did not develop steatosis, and had a trend towards increased plasma ketones when fasted." (PMID 34588527, 2021). "However, most phenotypic predictors of metabolic insulin resistance do not predict microvascular insulin responsiveness." (PMID 34075130, 2021). "Therefore, the authors concluded that high fasting plasma insulin concentrations were not a reflection of insulin resistance but rather the consequence of a basal hypersecretion of insulin relative to the degree of insulin resistance." (PMID 34360563, 2021). "A sedentary lifestyle and a high-calorie diet may play a role in increasing insulin resistance and blood insulin level (independent of obesity) in PCOS women." (PMID 33743611, 2021).